NFE2L1 (NFE2 like bZIP transcription factor 1)
Description:
[Endoplasmic reticulum membrane sensor NFE2L1]: Endoplasmic reticulum membrane sensor that translocates into the nucleus in response to various stresses to act as a transcription factor. Constitutes a precursor of the transcription factor NRF1 (By similarity). Able to detect various cellular stresses, such as cholesterol excess, oxidative stress or proteasome inhibition. In response to stress, it is released from the endoplasmic reticulum membrane following cleavage by the protease DDI2 and translocates into the nucleus to form the transcription factor NRF1 (By similarity). Acts as a key sensor of cholesterol excess: in excess cholesterol conditions, the endoplasmic reticulum membrane form of the protein directly binds cholesterol via its CRAC motif, preventing cleavage and release of the transcription factor NRF1, thereby allowing expression of genes promoting cholesterol removal, such as CD36 (By similarity). Involved in proteasome homeostasis: in response to proteasome inhibition, it is released from the endoplasmic reticulum membrane, translocates to the nucleus and activates expression of genes encoding proteasome subunits. [Transcription factor NRF1]: CNC-type bZIP family transcription factor that translocates to the nucleus and regulates expression of target genes in response to various stresses. Heterodimerizes with small-Maf proteins (MAFF, MAFG or MAFK) and binds DNA motifs including the antioxidant response elements (AREs), which regulate expression of genes involved in oxidative stress response. Activates or represses expression of target genes, depending on the context. Plays a key role in cholesterol homeostasis by acting as a sensor of cholesterol excess: in low cholesterol conditions, translocates into the nucleus and represses expression of genes involved in defense against cholesterol excess, such as CD36 (By similarity). In excess cholesterol conditions, the endoplasmic reticulum membrane form of the protein directly binds cholesterol via its CRAC motif, preventing cleavage and release of the transcription factor NRF1, thereby allowing expression of genes promoting cholesterol removal (By similarity). Critical for redox balance in response to oxidative stress: acts by binding the AREs motifs on promoters and mediating activation of oxidative stress response genes, such as GCLC, GCLM, GSS, MT1 and MT2 (By similarity). Plays an essential role during fetal liver hematopoiesis: probably has a protective function against oxidative stress and is involved in lipid homeostasis in the liver (By similarity). Involved in proteasome homeostasis: in response to proteasome inhibition, mediates the 'bounce-back' of proteasome subunits by translocating into the nucleus and activating expression of genes encoding proteasome subunits. Also involved in regulating glucose flux (By similarity). Together with CEBPB; represses expression of DSPP during odontoblast differentiation. In response to ascorbic acid induction, activates expression of SP7/Osterix in osteoblasts.
Synonyms: LCR-F1; NRF1; TCF11; FLJ00380; NRF-1
Tractability: Antibody: UniProt predicts a signal peptide or a membrane-spanning region. PROTAC: UniProt records ubiquitination sites on it; ubiquitination databases record sites on it.
Gene: Protein-coding gene on chromosome 17 (48,047,889 to 48,061,545, forward strand). Ensembl gene ENSG00000082641.
Subcellular location: Endoplasmic reticulum membrane (Endoplasmic reticulum membrane sensor NFE2L1); Endoplasmic reticulum membrane; Nucleus (Transcription factor NRF1)
Subcellular location (Human Protein Atlas): Nucleoplasm; Cytosol
Gene Ontology:
Molecular function: identical protein binding; protein binding; DNA-binding transcription factor activity; DNA-binding transcription factor activity, RNA polymerase II-specific; RNA polymerase II cis-regulatory region sequence-specific DNA binding; cholesterol binding; chromatin binding; DNA binding; DNA-binding transcription activator activity, RNA polymerase II-specific; promoter-specific chromatin binding; protein domain specific binding; protein-containing complex binding
Biological process: anatomical structure morphogenesis; heme biosynthetic process; regulation of transcription by RNA polymerase II; positive regulation of transcription by RNA polymerase II; regulation of DNA-templated transcription
Cellular component: endoplasmic reticulum membrane; nucleus; chromatin; endoplasmic reticulum; protein-containing complex
Genetic constraint (gnomAD): Loss-of-function variants: 18 observed, 64.03 expected, observed/expected ratio (o/e) 0.28, 90% interval 0.19 to 0.42. The upper end of that interval is the gene's LOEUF score, 0.42, which puts it in group 1 of 6, group 1 being the genes least tolerant of losing a copy. Missense variants: 827 observed, 1,021.5 expected, observed/expected ratio (o/e) 0.81, 90% interval 0.76 to 0.86. Synonymous variants: 419 observed, 424.33 expected, observed/expected ratio (o/e) 0.99, 90% interval 0.91 to 1.07.
Homologues: Orthologues: chimpanzee NFE2L1 (99% identical), macaque NFE2L1 (99% identical), rabbit NFE2L1 (97% identical), dog NFE2L1 (97% identical), pig NFE2L1 (96% identical), mouse Nfe2l1 (93% identical), rat Nfe2l1 (93% identical), guinea pig NFE2L1 (82% identical), tropical clawed frog nfe2l1 (60% identical), zebrafish nfe2l1a (41% identical), zebrafish nfe2l1b (14% identical). Paralogues in human: NFE2L3 (29% identical), NFE2L2 (21% identical), NFE2 (17% identical).
Diseases named in the same sentence as NFE2L1 in open-access papers:
NFE2L1 is named in the same sentence as 73 diseases in open-access papers, as found by Europe PMC text mining. Sharing a sentence is not in itself a finding about the gene and the disease. The quoted sentences say what the papers report.
hepatoma (9 papers, 2016 to 2024). "Wnt/β-catenin-dependent and -independent signaling networks were significantly inhibited in NFE2L1-deficient hepatocellular carcinoma HepG2 cells." (PMID 39061827, 2024). "The NFE2L1-high/NDUFA9-low group was more enriched in EMT signature genes than the other group, implying that the NDUFA9-associated NFE2L1 expression may play a key role in hepatoma cell invasiveness." (PMID 32942643, 2020). "Thus, we asked whether the NDUFA9-associated NFE2L1 expression contributed to hepatoma cell invasiveness." (PMID 32942643, 2020). "In hepatoma cells, NFE2L1 has also been shown to function as a mitochondrial retrograde gene that drives invasion and hepatic progression." (PMID 38562019, 2024). "Liver-specific Nfe2l1 deficiency in adult mice leads to severe NAFLD, even hepatocellular carcinoma." (PMID 39061827, 2024). "STX12 was upregulated through the ROS/STAT3/NFE2L1 axis in hepatoma cells, and it was a key downstream effector of NFE2L1 in modulating hepatoma cell invasiveness." (PMID 36400805, 2022). "Collectively, our results indicate that NFE2L1 is a key mitochondrial retrograde signaling-mediated primary gene product enhancing hepatoma cell invasiveness via STX12 expression and promoting liver cancer progression." (PMID 32942643, 2020). "NFE2L1 is one of the commonly upregulated TFs and a potential regulator of hepatoma cell invasiveness." (PMID 32942643, 2020). "The present study demonstrates that NFE2L1 is one of the reprogrammed gene products critically involved in hepatoma cell invasiveness via the expression of STX12." (PMID 32942643, 2020). "To elucidate the functional and mechanistic involvement of NFE2L1 in hepatoma cell activity, we examined protein levels in several hepatoma cell lines with (SNU354 and SNU423) or without (SNU387 and Ch-L) mitochondrial defects." (PMID 32942643, 2020). "We identified syntaxin 12 (STX12) as an effective downstream target of NFE2L1 by performing cDNA microarray analysis after the overexpression and depletion of NFE2L1 in hepatoma cells." (PMID 32942643, 2020). "The positive association between NFE2L1 and STX12 expression was validated by immunohistochemistry of the hepatocellular carcinoma tissue array." (PMID 32942643, 2020). "Compared to SNU387 and Ch-L cells, SNU354 and SNU423 hepatoma cells had higher NFE2L1 protein levels, corresponding to the NFE2L1 mRNA level." (PMID 32942643, 2020). "Our recent work has unraveled that knockout of the human full-length Nrf1α (including TCF11 and its derivates, collectively called Nrf1α−/−) by its Nfe2l1 gene editing from hepatoma cells leads to aberrant accumulation of Nrf2." (PMID 32273945, 2020). "In this study, we presented STX12 as a key downstream driver of NFE2L1 to induce hepatoma cell invasiveness." (PMID 32942643, 2020). "We further demonstrated that STX12 is upregulated through the ROS/STAT3/NFE2L1 axis and is a key downstream effector of NFE2L1 in modulating hepatoma cell invasiveness." (PMID 32942643, 2020). "Collectively, our results indicate that NFE2L1 is a key mitochondrial retrograde signaling-mediated gene product enhancing hepatoma cell invasiveness via STX12 expression." (PMID 32942643, 2020). "Although NFE2L1, which is synthesized de novo in response to mitochondrial dysfunction, has been shown to control hepatoma cell invasion activity, NFE2L1 itself is a TF." (PMID 32942643, 2020). "Furthermore, in liver-specific knockout mice, Nfe2l1 depletion also resulted in hepatoma formation, including hepatocellular carcinoma and adenoma." (PMID 39061827, 2024). "The transcriptome, metabolome, and seahorse data further revealed that disruption of NFE2L1 could reprogram glucose metabolism to aggravate the Warburg effect in NFE2L1-silenced hepatoma cells, concomitant with mitochondrial damage." (PMID 35614059, 2022). "However, hepatocyte-specific NFE2L1-knockout mice exhibit severe hepatic steatosis and liver carcinoma." (PMID 32942643, 2020).
hepatoma (continued). "This suggests that NFE2L1 cannot directly regulate the invasion activity and manifests its controlling power via the synthesis of secondary effector molecule(s) responsible for the hepatoma cell invasiveness." (PMID 32942643, 2020). "NFE2L1 is the key transcription factor to enhance hepatoma cell invasiveness via STX12 expression." (PMID 32942643, 2020). "Taken together, these results indicate that NFE2L1/STX12 expression is the key to regulating hepatoma cell invasiveness and may be useful as a prognostic marker for HCC." (PMID 32942643, 2020). "Taken together, these results indicate that NFE2L1 is a key regulator of hepatoma cell invasiveness, and NDUFA9 depletion is an upstream driver of OXPHOS defect and NFE2L1 upregulation in HCC tumors." (PMID 32942643, 2020). "Nuclear factor-erythroid 2 like 1 (NFE2L1), also known as NRF1, is another key transcription factor that can promote hepatoma cell invasiveness via the STAT3/NFE2L1/STX12 axis." (PMID 34440674, 2021). "In this study, we demonstrate that the mitochondrial OXPHOS defect enhances NFE2L1 transcription via reactive oxygen species (ROS)-mediated STAT3 activation, and the upregulation of NFE2L1 increased hepatoma cell invasiveness by inducing syntaxin 12 (STX12) expression." (PMID 32942643, 2020). "However, our results clearly demonstrate that augmented NFE2L1 expression grants invasion activity to immortalized liver cells (Ch-L) and non-aggressive hepatoma cells (SNU387), suggesting a differential role of NFE2L1 according to cellular context." (PMID 32942643, 2020).
Obesity (6 papers, 2019 to 2024). Accumulation of substantial excess body fat. "The NFE2L1 gene is also associated with obesity, and NFE2L2 overexpression results in weight loss and protection against diet‐induced obesity in transgenic mice." (PMID 38562019, 2024). "The single nucleotide polymorphism on the 5′-flanking regions of the NFE2L1 has been associated with obesity." (PMID 35614059, 2022). "The NFE2L1 gene on chromosome ECA11 is associated with lipid metabolism and obesity in humans and mice." (PMID 37510415, 2023). "In adipocytes, knockout of NFE2L1 results in disappearance of subcutaneous adipose tissue, accompanied by insulin resistance, adipocyte hypertrophy, and obesity-related inflammation." (PMID 35614059, 2022). "In contrast, NFE2L1 transgenic mice present with impaired glucose metabolism in the liver and insulin resistance in a diet-induced obesity model." (PMID 32942643, 2020). "Nfe2l1 has great potential to be a therapy target of diabetes and obesity and may be a ligand of many natural and synthetic compounds." (PMID 30641913, 2019).
liver cancer (5 papers, 2020 to 2025). An epithelial or non-epithelial malignant neoplasm that arises from the liver. "The 41BBL protein is a possible oxidative stress-responsive immune checkpoint, which was directly regulated by NFE2L1 in HepG2 human liver cancer cells." (PMID 39061827, 2024). "However, this contradicts our previous finding that NFE2L1 promotes the malignant progression of liver cancer, a discovery that is worth considering." (PMID 40677211, 2025). "Furthermore, liver cancer tissues express both NFE2L1 and 41BBL at low levels, suggesting that 41BBL may be related to the formation of HCC brought on by NFE2L1 deletion." (PMID 37238995, 2023). "Next, to validate the relationship between NFE2L1 and STX12 protein expression, we performed immunohistochemistry using a liver cancer tissue array." (PMID 32942643, 2020). "NFE2L1 may regulate TAM polarization in tumorigenesis, with its role differing in liver cancer and glioma, acting as a double‐edged sword in cancer development and providing insights into its mechanisms in various pathologies." (PMID 40677211, 2025). "Our study presents a novel mitochondrial dysfunction-mediated retrograde signaling pathway and the resulting transcriptomic reprogramming in liver cancer progression, providing the NDUFA9/NFE2L1/STX12 axis as a key prognostic marker of aggressive liver cancer with mitochondrial defects." (PMID 32942643, 2020). "However, current research on cancer proliferation is mainly conducted in liver cancer, and the role of NFE2L1 in other types of cancers is not yet clear." (PMID 39061827, 2024). "Interestingly, liver-specific NFE2L1 inactivation results in steatohepatitis, fibrosis, and the spontaneous development of hepatic neoplasia in mice, implying its potential negative involvement in liver cancer development." (PMID 32942643, 2020).
Insulin resistance (3 papers, 2020 to 2022). Increased resistance towards insulin, that is, diminished effectiveness of insulin in reducing blood glucose levels. "The results of NFE2L1 deficiency may interfere with the expression of lipolysis genes in adipocytes, lead to adipocyte hypertrophy, and then lead to inflammation, cell pyrogenesis and insulin resistance." (PMID 34944373, 2021).
insulinoma (3 papers, 2024 to 2025). "Similar mitochondrial dysfunction was observed when NFE2L1 was knocked out in hepatic cells and insulinoma cells, where NFE2L1 deficiency resulted in dysregulation of the mitochondrial respiratory chain and increased mitochondrial membrane potential." (PMID 40375958, 2025). "NFE2L1 knockdown was also shown to promote insulinoma cell proliferation and invasion in vitro and chemoresistance in a murine allograft transplantation model, highlighting NFE2L1 as a potential tumor suppressor." (PMID 38562019, 2024). "Overexpressed HK1 in Nfe2l1-KD insulinoma cells attached to the mitochondria to block mitochondrial toxicant-induced cytotoxicity and apoptosis." (PMID 39061827, 2024). "In a transplantation tumor model, Nfe2l1-KD insulinoma MIN6 cells grew faster and developed resistance to streptozotocin (STZ) and 5-fluorouracil." (PMID 39061827, 2024).
lung adenocarcinoma (3 papers, 2021 to 2023). A carcinoma that arises from the lung and is characterized by the presence of malignant glandular epithelial cells. "Therefore, we performed an evaluation of the effects of T3, TOS, and T3E on NFE2L1 and sensitivity to bortezomib in the lung adenocarcinoma cell line, A549, and the pancreatic cancer cell line, PANC1." (PMID 37298331, 2023). "The recent research also reported that NFE2L1 could regulate lung adenocarcinoma progression through Wnt pathway." (PMID 34536977, 2021).
non-alcoholic steatohepatitis (3 papers, 2014 to 2024). "Liver-specific deletion of NFE2L1 in mice leads to pathological features similar to those of human nonalcoholic steatohepatitis (NASH)." (PMID 37759569, 2023). "Moreover, conditional knockout of Nrf1 (also called nfe2l1) in the liver, brain and bone results in non-alcoholic steatohepatitis (NASH) and hepatoma, neurodegeneration, and reduced bone size." (PMID 25290918, 2014).
breast carcinoma (2 papers, 2024 to 2025). "Furthermore, in breast cancer cells, it was demonstrated that NFE2L1 played the critical role in evading T-cell killing by upregulating super-enhancer-mediated PD-L1 expression." (PMID 39061827, 2024). "In breast cancer cells, PKM2 controls NFE2L1 cleavage and the transcriptional downstream transmembrane protein 33 (TMEM33), which regulates activation of SREBPs and lipid metabolism." (PMID 39061827, 2024).
diabetes (2 papers, 2019 to 2022). "Previous studies have shown that mice with NFE2L1 overexpression or knockout exhibit diabetes-like phenotypes." (PMID 35614059, 2022). "The overexpression of NFE2L1 eventually developed into diabetes mellitus in transgenic mice." (PMID 35614059, 2022).
fibrosarcoma (2 papers, 2020 to 2024). A malignant mesenchymal fibroblastic neoplasm affecting the soft tissue and bone. "GPX4 is necessary for NFE2L1-mediated ferroptosis resistance in HT-1080 fibrosarcoma cells and sufficient to rescue ferroptosis resistance in NFE2L1 gene-disrupted A549 cells." (PMID 39025451, 2024). "In contrast, lncRNA promoters were enriched for MAFG:NFE2L1 (V-Maf Avian Musculoaponeurotic Fibrosarcoma Oncogene Homolog G:Nuclear Factor, Erythroid 2 Like 1) motifs." (PMID 32005828, 2020).
Multiple Myeloma (2 papers, 2020 to 2024). "In addition, NFE2L1 mediates the proteasome bounce-back effect in the clinical proteasome inhibitor therapy of neuroblastoma, multiple myeloma, and triple-negative breast cancer, which quickly induces proteasome inhibitor resistance." (PMID 39061827, 2024).
Parkinson's (2 papers, 2019 to 2025). "Parkinson’s disease, a neurodegenerative disorder characterized by the loss of dopaminergic neurons in the substantia nigra (SN), has been linked to deficits in NFE2L1 expression." (PMID 40375958, 2025). "It was revealed that Pbx1 provides a beneficial effect of protecting against oxidative stress by increasing Nfe2l1 (also called NRF1), and decreasing levels of both TFs were found in midbrain dopaminergic neurons of Parkinson's patients." (PMID 31584878, 2019).
prostate carcinoma (2 papers, 2017 to 2024). A carcinoma that arises from epithelial cells of the prostate gland. "In prostate cancer, excessive ROS induce NFE2L1 activation and regulate downstream antioxidant genes, such as peroxiredoxin 1 (Prx-1) and thioredoxin 1 (Txn-1), which compensate for oxidative stress and maintain redox homeostasis." (PMID 39061827, 2024). "However, downregulation of NFE2L1 has been found in ovarian and prostate cancers." (PMID 39061827, 2024). "Moreover, 8 of these TFs (FOXJ2, GATA6, NFE2L1, NFIL3, PRRX2, TEF, EBF2 and ZBTB18) were found to be differentially expressed in this study making them not only candidate biomarkers of prostate cancer but also potential therapeutic targets." (PMID 28380430, 2017).
Alzheimer disease (1 paper, 2025). A progressive, neurodegenerative disease characterized by loss of function and death of nerve cells in several areas of the brain leading to loss of cognitive function such as memory and language. "In Alzheimer’s disease, a progressive neurodegenerative disorder marked by cognitive decline and amyloid-beta plaques, NFE2L1 expression has also been implicated." (PMID 40375958, 2025).